MYO7A (myosin VIIA)
Description:
Myosins are actin-based motor molecules with ATPase activity. Unconventional myosins serve in intracellular movements. Their highly divergent tails bind to membranous compartments, which are then moved relative to actin filaments. In the retina, plays an important role in the renewal of the outer photoreceptor disks. Plays an important role in the distribution and migration of retinal pigment epithelial (RPE) melanosomes and phagosomes, and in the regulation of opsin transport in retinal photoreceptors. In the inner ear, plays an important role in differentiation, morphogenesis and organization of cochlear hair cell bundles. Involved in hair-cell vesicle trafficking of aminoglycosides, which are known to induce ototoxicity (By similarity). Motor protein that is a part of the functional network formed by USH1C, USH1G, CDH23 and MYO7A that mediates mechanotransduction in cochlear hair cells. Required for normal hearing.
Synonyms: USH1B; NSRD2; DFNA11; DFNB2; MYOVIIA; MYU7A
Tractability: PROTAC: ubiquitination databases record sites on it.
Gene: Protein-coding gene on chromosome 11 (77,128,245 to 77,215,241, forward strand). Ensembl gene ENSG00000137474.
Subcellular location: Cytoplasm; Cytoplasm, cell cortex; Cytoplasm, cytoskeleton; Synapse
Pathways (Reactome):
Sensory Perception: Sensory processing of sound by inner hair cells of the cochlea; Sensory processing of sound by outer hair cells of the cochlea; The canonical retinoid cycle in rods (twilight vision)
Gene Ontology:
Molecular function: actin filament binding; calmodulin binding; microfilament motor activity; protein binding; spectrin binding; ATP binding; cytoskeletal motor activity; protein domain specific binding
Biological process: actin filament-based movement; equilibrioception; lysosome organization; sensory perception of light stimulus; sensory perception of sound; visual perception; endocytosis; eye photoreceptor cell development; intracellular protein localization; mechanoreceptor differentiation; sensory organ development; neuron development; sensory organ morphogenesis
Cellular component: cytoplasm; cytosol; lysosomal membrane; photoreceptor inner segment; photoreceptor outer segment; synapse; actin cytoskeleton; microvillus; stereocilium; stereocilium base; apical plasma membrane; cell cortex; cytoskeleton; melanosome; membrane; myosin complex; photoreceptor cell cilium; photoreceptor connecting cilium
Genetic constraint (gnomAD): Loss-of-function variants: 209 observed, 235.52 expected, observed/expected ratio (o/e) 0.89, 90% interval 0.79 to 1. The upper end of that interval is the gene's LOEUF score, 1, which puts it in group 4 of 6, group 1 being the genes least tolerant of losing a copy. Missense variants: 2,820 observed, 2,831.2 expected, observed/expected ratio (o/e) 1, 90% interval 0.96 to 1.03. Synonymous variants: 1,238 observed, 1,124.1 expected, observed/expected ratio (o/e) 1.1, 90% interval 1.05 to 1.15.
Gene-disease validity (ClinGen):
ClinGen rates the evidence that MYO7A causes each of these diseases.
nonsyndromic genetic hearing loss (autosomal dominant): Definitive. A disease characterized by hearing loss that is not part of a larger syndrome.
Usher syndrome type 1 (autosomal recessive): Definitive. A syndrome characterized by congenital, bilateral, severe sensorineural hearing loss, abnormalities in the vestibular system, and adolescent-onset retinitis pigmentosa.
Homologues: Orthologues: macaque MYO7A (99% identical), chimpanzee MYO7A (99% identical), dog MYO7A (98% identical), pig MYO7A (97% identical), guinea pig MYO7A (97% identical), mouse Myo7a (95% identical), rat Myo7a (94% identical), rabbit MYO7A (93% identical), tropical clawed frog myo7a (86% identical), zebrafish myo7aa (83% identical), Drosophila melanogaster ck (62% identical). Paralogues in human: MYO7B (52% identical), MYO15A (27% identical), MYO10 (25% identical), MYH6 (22% identical), MYH7 (21% identical), MYH2 (21% identical), MYH3 (21% identical), MYH7B (21% identical), MYH1 (21% identical), MYH8 (21% identical), MYH4 (20% identical), MYH13 (20% identical), and 32 more.
Diseases named in the same sentence as MYO7A in open-access papers:
MYO7A is named in the same sentence as 102 diseases in open-access papers, as found by Europe PMC text mining. Sharing a sentence is not in itself a finding about the gene and the disease. The quoted sentences say what the papers report.
Usher syndrome (143 papers, 2004 to 2026). A syndromic diseae characterized by the association of sensorineural deafness (usually congenital) with retinitis pigmentosa and progressive vision loss. "MYO7A is a causal gene, underlying Usher syndrome type 1B (USH1B) and both autosomal recessive (DFNB2) and dominant (DFNA11) non-syndromic hearing loss." (PMID 41852313, 2026). "Defective myo7a and cdh23, to a lesser extent, cause Usher Syndrome Type 1B (USH1B), which is characterized by deafness and reduced vestibular function." (PMID 40463242, 2025). "Of note, affected individuals homozygous for the MYO7A variants had a phenotype compatible with Usher syndrome type 1, including congenital deafness." (PMID 40180963, 2025). "Segregation analysis in both parents confirmed the MYO7A variants to be biallelic and therefore causative for the Usher syndrome phenotype." (PMID 40269797, 2025). "By contrast, patients carrying MYO7A variants exhibited both RP and hearing impairment, aligning with the diagnosis of Usher syndrome." (PMID 38245557, 2024). "SNHL due to MYO7A variants, although associated with Usher Syndrome, can also present in an autosomal dominant fashion, leading to non-syndromic post-lingual moderate, progressive SNHL." (PMID 39062005, 2024). "Fifty-three patients (mean age, 33.6 ± 16.7 years) with Usher syndrome owing to biallelic, mostly pathogenic, variants in MYO7A underwent baseline and two annual follow-up visits." (PMID 38884554, 2024). "Whilst suitable for a number of ciliopathy-related genes, such as RPGR (3.5 kb), many genes are beyond this capacity, including CEP290 (7.4 kb) and several of the Usher-syndrome-associated genes (MYO7A: 6.6 kb, CDH23: 10 kb, ADGRV1: 18.9 kb, USH2A: 15.6 kb)." (PMID 38474133, 2024). "Ten patients with a genetically confirmed retinitis pigmentosa in Usher syndrome due to biallelic variants in MYO7A or USH2A were enrolled in the study." (PMID 38984112, 2024). "Comparing the disease progression with the second most frequent gene causing Usher syndrome, MYO7A, on average, MYO7A patients reach legal blindness at a younger age." (PMID 36980924, 2023). "For instance, mutations of MYO7A were found to be responsible for Usher syndrome, a brain-related disease." (PMID 36970281, 2023). "Mutations in MYO7A are known to cause Type 1 Usher Syndrome, a condition characterised by deafness and retinal degeneration." (PMID 36848389, 2023). "The two couples were carriers of pathogenic variants in the MYO7A gene (Usher syndrome) and RNASEH2B (Aicardi-Goutières syndrome)." (PMID 36406136, 2022). "MYO7A is associated with Usher syndrome, type 1B (OMIM #276900), an autosomal recessive disorder characterized by retinitis pigmentosa, vestibular dysfunction, and hearing loss." (PMID 35761346, 2022). "Mutations in USH2A and MYO7A were responsible for two-thirds of solved cases (48% and 20%, respectively), in line with the high prevalence of Usher syndrome patients (78.6% of syndromic cases)." (PMID 36460718, 2022). "Mutations in MYO7A have been linked to Usher syndrome, a condition denoted by hearing loss and RP, and defects in RPE phagocytosis of rod OS." (PMID 35758026, 2022). "Mutations in the MYO7A gene lead to Usher syndrome type 1B (USH1B), a disease characterized by congenital deafness, vision loss, and balance impairment." (PMID 35710827, 2022). "The most common form of Usher syndrome is Usher type 1B, which is caused by myosin VIIa (MYO7A) mutation that is expressed in the RPE, and PR connecting cilium and synapse." (PMID 36476500, 2022). "Usher syndrome, most frequently due to biallelic variants in MYO7A (USH1B in 16 probands), USH2A (17 probands), and ADGRV1 (USH2C in 7 probands), was diagnosed in 44 of 59 (75%) unrelated probands." (PMID 34148116, 2022). "Variants in the MYO7A gene are increasingly identified among patients suffering from Usher syndrome type 1B (USH1B)." (PMID 36164746, 2022).
Usher syndrome (continued). "Three patients with syndromic SNHI, including one with Usher syndrome (MYO7A variants), one with LEOPARD syndrome (PTPN11 variant), and one with DiGeorge syndrome (TBX1 variant) exhibited unfavorable outcomes with CI." (PMID 36009393, 2022). "Myosin VIIA is a protein linked to hair bundle formation and mechanotransduction, and mutations in MYO7A are also related to Usher syndrome and DFNB2." (PMID 33613440, 2021). "Identification of genetic mutations in the Myo7a gene, associated with retinal degeneration in Usher syndrome, suggests that unconventional myosins play a critical role in retinal pigmented epithelium (RPE) and photoreceptor cell function." (PMID 34073294, 2021). "Usher syndrome type 1B (USH1B) is a genetic disorder caused by mutations in the unconventional Myosin VIIa (MYO7A) protein." (PMID 33889793, 2021). "Usher syndrome in humans is mainly caused by missense variants and inframe deletions affecting various essential amino acids in the MYO7A protein." (PMID 33955556, 2021). "PCDH15, CDH23 and MYO7A: While these three genes are known for Usher syndrome, they have AR nonsyndromic forms of hearing loss." (PMID 33924653, 2021). "Since mutations or deletion of the motor protein, MYO7A, were associated with retinal degeneration in Usher syndrome and its animal model, we were prompted to investigate the effect of Myo1c in retinal function." (PMID 34073294, 2021). "Mutations in myosin-VIIa (MYO7A) cause Usher syndrome type 1, characterized by combined deafness and blindness." (PMID 32350269, 2020). "Family 8 revealed three different heterozygous variants in MYO7A, with all three of them exclusively present in both affected siblings (IV.1, IV.2), in whom Usher syndrome was excluded." (PMID 33187236, 2020). "Usher syndrome is a ciliopathy or disorder caused by a defect in ciliary protein trafficking, and many of the Usher gene protein products, including myosin VIIa, cadherin 23, usherin, and harmonin, are thought to be expressed in retinal ganglion cells." (PMID 33083048, 2020). "To date, 10 causative genes have been identified for Usher syndrome, with MYO7A accounting for >50% of type 1 and USH2A contributing to approximately 80% of type 2 Usher syndrome." (PMID 32995707, 2020). "Different compound heterozygous or homozygous mutations related to MYO7A have been reported in a variety of autosomal recessive Usher Syndrome families." (PMID 31898538, 2020). "The proteins encoded by these mutant genes, whirlin and myosin VIIA, are among several Usher syndrome proteins found to interact with usherin at the mouse periciliary membrane complex." (PMID 31998945, 2020). "Patients diagnosed with Usher syndrome type 1B having MYO7A variants typically show profound hearing loss at birth and progressive retinal degeneration." (PMID 30733538, 2019). "More than 340 different variants in myosin VIIA have been reported to be related to congenital syndrome deafness with retinitis pigmentosa (Usher syndrome) type 1 and type 2." (PMID 31250571, 2019). "The biological function of Myo7a was mainly found to be associated with Usher Syndrome, Type I and Deafness." (PMID 30719228, 2019). "From the arRP patient cohort, 6 patients presented with syndromic disease: 2 with Usher syndrome type 1 (caused by MYO7A) and 4 with Usher syndrome type 2 (3 with disease caused by USH2A and 1 with GPR98)." (PMID 31341231, 2019). "Usher’s syndrome is the most common combined blindness–deafness disorder with USH1B, caused by mutations in MYO7A, resulting in the most severe phenotype." (PMID 31824252, 2019). "The MYO7A gene mutations have been reported as the cause of Usher syndrome type 1B (USH1B), a syndromic deafness combined with retinitis pigmentosa and vestibular abnormalities." (PMID 30123251, 2018). "To date, more than 160 different mutations of MYO7A gene have been identified, most of which have been reported to induce Usher syndrome type IB and nonsyndromic Usher syndrome." (PMID 29692870, 2018).
Usher syndrome (continued). "Mutations in the MYO7A gene have been identified to be associated with nonsyndromic hearing loss (DFNB2, DFNA11) and Usher Syndrome type 1B (USH1B)." (PMID 29568747, 2018). "This is insufficient for certain diseases, such as Usher Syndrome Type 1B (USH1B) caused by mutations in the MYO7A gene (of which the cDNA is 7 kb long), and Stargardt disease caused by mutations in the ABCA4 gene (of which the cDNA is 7.3 kb long)." (PMID 30486314, 2018). "Mutations within MYO7A can lead to either non syndromic hearing loss or to the Usher syndrome type 1B (USH1B)." (PMID 28472130, 2017). "Polarized inner ear hair cells are affected by deficiencies in protein trafficking and collagen homeostasis; mutations in the unconventional myosins, for example, myosin VIIA, lead to sensorineural deafness in Usher syndrome (OMIM." (PMID 28017832, 2017). "Defects in MYO7A have been shown to cause Usher syndrome, a disorder characterized by sensorineural hearing loss combined with retinitis pigmentosa." (PMID 26837541, 2016). "Pathogenic variants of MYO7A, the human homologue of myosin VIIa, can cause Usher syndrome, the leading cause of deaf-blindness, as well as the non-syndromic forms of deafness DFNA11 and DFNB2." (PMID 27331610, 2016). "Mutations in the gene that produces one of these proteins, called myosin VIIa, cause an inherited deaf-blind disorder called Usher syndrome." (PMID 27331610, 2016). "Analysis of the variant list from case 863 (a female) identified missense variants in GPR98 and MYO7A as the best candidates even though mutations in these genes usually cause recessive Usher syndrome." (PMID 25133751, 2014). "We report here four patients, who had probable pathogenic mutations in two different Usher syndrome type 1 genes, and one case of MYO7A/PCDH15 digenic inheritance." (PMID 24618850, 2014). "Usher syndrome type 1B is a combined deaf-blindness condition caused by mutations in the MYO7A gene." (PMID 24705452, 2014). "Today, the vast majority of mutations in the MYO7A are associated with autosomal recessive hearing loss or Usher syndrome." (PMID 23383098, 2013). "Myosin VIIA has been implicated in Usher syndrome type 1B, atypical Usher syndrome, non-syndromic autosomal recessive hearing impairment (DFNB2) and autosomal dominant hearing impairment (DFNA11)." (PMID 23383098, 2013). "Myosin VIIA mutations have been described in vertebrates, including those causing the Usher syndrome in humans, the shaker-1 mutation in mice, and the mariner mutation in zebrafish." (PMID 15596016, 2004). "Similarly, the prevalence of MYO7A-associated ARNSHL patients in autosomal recessive or sporadic HL patients was 0.38% (25/6163), and 0.32% (21/6163) for cases of MYO7A-associated Usher syndrome." (PMID 38594301, 2024). "The pathogenic variant c.920_923dup p.(His308Glnfs*16) was the most frequently encountered variant in USH2A-associated Usher syndrome (n = 5/5; families/patients), while c.397dup p.(His133Profs*7) was the most frequent variant for MYO7A-associated cases (n = 4/7; families/patients)." (PMID 38189974, 2024). "Some variants of MYO7A are associated with Usher syndrome type 1." (PMID 38562617, 2024). "Moreover, MYO7A (OMIM: 276903) is associated with Usher Syndrome type 1B (OMIN: 276900), ARNSHI (OMIM: 600060), and ADNSHI (OMIM: 601317), and PLP variants in this gene were found in Fam8." (PMID 35440622, 2022). "Further, one report suggested that DFNB2 and Usher syndrome patients may share the same mutations in MYO7A‐mutated families." (PMID 36164746, 2022). "Interestingly, mutations in MYO7A gene can be responsible for nonsyndromic recessive or dominant hearing loss, as well as for syndromic forms, such as in Usher syndrome." (PMID 35076463, 2022). "Some Usher syndrome patients were found to carry mutations in MYO7A, and PCDH15 genes." (PMID 34609590, 2022). "Mutations in MYO7A are associated with Usher Syndrome type 1B (USH1B)." (PMID 34722588, 2021).